MIR365B (microRNA 365b)
Synonyms: hsa-mir-365-2; MIR365-2; MIRN365-2; hsa-mir-365b; mir-365b
Gene: MicroRNA gene on chromosome 17 (31,575,411 to 31,575,521, forward strand). Ensembl gene ENSG00000283978.
Gene Ontology:
Cellular component: RISC complex
Homologues: Orthologues: chimpanzee ptr-mir-365-2 (100% identical), dog MIR365B (100% identical), macaque mml-mir-365-2 (99% identical), guinea pig MIR365B (97% identical), rat Mir365b (88% identical), rabbit MIR365B (87% identical), zebrafish dre-mir-365-2 (77% identical), zebrafish dre-mir-365-3 (77% identical), pig ssc-mir-365-2 (74% identical). Paralogues in human: MIR365A (65% identical).
Diseases named in the same sentence as MIR365B in open-access papers:
MIR365B is named in the same sentence as 2 diseases in open-access papers, as found by Europe PMC text mining. Sharing a sentence is not in itself a finding about the gene and the disease. The quoted sentences say what the papers report.
tumour (1 paper, 2017). "The MIR365B gene, locatedwithin the NF1 microdeletion region, also encodes an miRNA withknown tumour suppressor function, as evidenced by its ability to target specifictranscription factors, such as NKX2-1 and TTF1, in non-small cell lung cancer." (PMID 28213670, 2017).
MIR365B also shares sentences with these, for which no sentence is quoted: intellectual disabilities (1 paper).